TNF (tumor necrosis factor)
Diseases named in the same sentence as TNF in open-access papers (continued):
Sharing a sentence is not in itself a finding about the gene and the disease.
spondyloarthritis (continued). "COAST-V and COAST-W were 52-week, phase 3, randomized controlled trials evaluating the efficacy and safety of ixekizumab in biologic disease-modifying antirheumatic drug (bDMARD)-naïve and tumor necrosis factor inhibitor (TNFi)-experienced patients with radiographic spondyloarthritis, respectively." (PMID 34538257, 2021). "Females also are less likely than males to adhere to treatment with TNF inhibitors for spondyloarthritis, with lack of efficacy and adverse events being associated with immunotherapy withdrawal among females." (PMID 32366281, 2020). "Among patients with spondyloarthritis, males have greater circulating concentrations of TNF than females, which may be one mechanisms mediating how TNF inhibitors are more effective treatments in males than females with either RA or spondyloarthritis." (PMID 32366281, 2020). "Preliminary data obtained from a clinical trial does not support this hypothesis for the moment as the effect observed in spondyloarthritis patients remains equivalent to those described previously with anti-TNF therapies." (PMID 31485194, 2019). "Four patients of our spondyloarthritis sub-cohort received anti-TNF therapy." (PMID 31337412, 2019). "In patients with RA and related spondyloarthropathies, IL-1 and TNFα are key contributors." (PMID 26885252, 2016). "The results of the trial may be useful in guiding the management of patients with spondyloarthropathies requiring anti-TNF treatment." (PMID 26289076, 2015). "Nevertheless, further studies are needed to determine whether relevant differences exist among the anti-TNF therapies in treatment of spondyloarthritis." (PMID 25110401, 2014). "Hence in this study we assessed, on the basis of retrospective data, the persistence of anti-TNF-α agents in a cohort of patients undergoing long-term treatment for spondyloarthritis in a real-life clinical setting." (PMID 25110401, 2014). "Also sleep apnea is less common in patients with spondyloarthritis who received TNF-inhibitor therapy." (PMID 25276055, 2014). "The failure to respond to TNF antagonists might be because this sclerosing bone-forming phenotype of spondyloarthropathy is less responsive to TNF antagonists than other more inflammatory phenotypes." (PMID 24330652, 2013). "Anti-TNF treatment in spondyloarthritis increased bone-specific alkaline phosphatase (BALP) and negative correlation between BALP and metalloproteinase-3 (bone destruction marker) was discovered, indicating that new bone formation in AS occurs if inflammation is depressed." (PMID 21627836, 2011). "Initiation of anti-TNF therapy in patients with very early AS or preradiographic spondyloarthritis may prevent radiographic progression in the spine, but there are no data as of yet to confirm this hypothesis." (PMID 19703304, 2009). "Therefore, TNF is a therapeutic target for a class of drugs used to treat spondyloarthropathy." (PMID 32938495, 2020). "Besides, higher CD154 expression could predict clinical efficacy of spondyloarthropathy patients with TNF-α blockade treatment." (PMID 28837666, 2017). "Treatment with non-steroidal anti-inflammatory drugs reduces radiographic evidence of spinal progression in spondyloarthritis after two years of follow up, and long-term treatment with anti-TNF agents may also provide some protection from progression of disease as evidenced by imaging studies." (PMID 27165410, 2016). "Additionally, patients with spondyloarthropathy or adult RA who responded favorably to the anti-TNF-α monoclonal antibody infliximab showed a rapid and marked decrease in the level of MRP-positive macrophages in tissue infiltrates, but not in the total population of resident macrophages." (PMID 21876832, 2011). "Its production is synergistically induced by TNF-α and IFN-γ in human microvascular endothelial cells, and its levels are notably elevated in the synovial fluids of patients with spondyloarthropathies." (PMID 40305235, 2025).
spondyloarthritis (continued). "The efficacy of anti-TNF therapies, particularly infliximab and adalimumab, is reaffirmed by our findings as these agents are crucial for patients with concurrent IBD and spondyloarthritis, particularly when standard treatments fail." (PMID 39768419, 2024). "Impaired humoral responses to PCV vaccination were also seen in patients with RA, spondyloarthropathies, or IBD taking TNF inhibitors, particularly in the presence of concomitant MTX." (PMID 35214755, 2022). "In the presence of spondyloarthropathy (SpA) or IBD accompanying FMF, as in our patient, anti-TNF agents are recommended as a treatment option." (PMID 34568239, 2021). "We did however note increased GM-CSF+ CD4 T cells in patients on anti-TNF therapy, but even with the exclusion of these patients from the analysis, GM-CSF+ CD4 cells were still elevated in spondyloarthritis compared to controls." (PMID 29142230, 2017). "The use of tumor necrosis factor (TNF) blockers has dramatically improved the clinical outcome and quality of life of patients with spondyloarthritis (SpA)." (PMID 25135077, 2014). "Tumor necrosis factor alpha (TNF-α) is a pro-inflammatory cytokine and considered one of important cytokines in the development of spondyloarthropathy (SpA)." (PMID 22470519, 2012). "Serum pro-inflammatory cytokine assays have been reported in spondyloarthritis patients treated with anti-TNF agents, but this is not standard care." (PMID 36960229, 2023). "Our study results are in line with two studies that observed no decrease in IL-17 blood levels in spondyloarthritis patients treated with TNF-inhibitors for 2 years and 6 months." (PMID 35203534, 2022). "ASAS, Assessment of SpondyloArthritis international Society; ASAS20, 20% improvement in ASAS criteria; BL, baseline; i.v., intravenous; q4wk, every 4 weeks; PBO, placebo; R, randomization; s.c., subcutaneous; TNF, tumor necrosis factor; wk, week." (PMID 29273067, 2017). "Decreased expression of TNFAIP3 in AxSpA macrophages correlated with increased LPS-induced TNF-α, and thus, TNFAIP3 dysregulation may be a contributor to excessive inflammatory responses in spondyloarthritis subjects." (PMID 28791018, 2017). "There was not a high prevalence of LLS in patients with spondyloarthritis treated with anti TNFα therapy." (PMID 22336076, 2012). "The anti-TNFα therapy has been since its approval by the FDA, along with nonsteroidal antiinflammatory drugs (NSAIDs), one of the most important therapies for control of spondyloarthritis (SpA)." (PMID 22336076, 2012). "In spondylarthropathy, however, patients gained fat during 2 years of treatment with TNF antagonists - but being without a control group, clarifying the role of anti-TNF versus control of the inflammatory activity was impossible." (PMID 20964833, 2010). "Therefore, studies in patients with spondyloarthritis with preradiographic sacroiliitis or early evidence of sacroiliitis (and who do not yet satisfy the modified New York criteria) may be more likely to demonstrate inhibition of structural damage following TNF antagonist therapy." (PMID 19703304, 2009). "Of 100 patients with spondyloarthritis, 51 were on anti-TNF-α drugs and 49 were not." (PMID 30942280, 2019). "The study on spondyloarthropathy was uncontrolled and could not differentiate between a specific effect of TNF antagonists and a general effect of reduced inflammatory activity." (PMID 20964833, 2010). "Rising levels of BALP and the negative correlation between MMP-3 and BALP in spondyloarthritis patients with TNF-α blocker treatment indicate that new bone formation in AS occurs if inflammation is successfully treated and might be part of a healing process." (PMID 18945353, 2008). "The inhibition of TNF production, when SFL were depleted of NK cells, was therefore stronger in samples from patients with RA (about 75% inhibition) than in synovial fluid from seronegative spondyloarthropathies (50%) or in samples from crystal-induced arthritis (30%)." (PMID 16684368, 2006).
hyperlipidemia (166 papers, 2010 to 2026). "Hyperlipidemia, linked to systemic inflammation, activates the NF-κB pathway, increasing pro-inflammatory cytokines like TNF-α and IL-6." (PMID 39768728, 2024). "Hyperlipidemia has been associated with increased levels of TNF-α, which promotes a chronic inflammatory state and can impair intestinal barrier function." (PMID 38132943, 2023). "Pro-inflammatory genes (TNF-α and IL-6) were reported to be expressed at high levels and to contribute to cardiovascular diseases caused by hyperlipidemia." (PMID 30049280, 2018). "Interestingly, hyperlipidemia using model mice is also involved in the higher expression of inflammatory cytokines such as IL-6 and TNF-α and alveolar bone loss, and therefore, hyperlipidemia would be a risk factor of inflammation in oral cavity." (PMID 41590174, 2026). "Chronic exposure to proinflammatory cytokines, such as TNF-α and IL-1β, may alter lipid metabolism, causing hyperlipidemia." (PMID 34203460, 2021). "Hyperlipidemia causes adipocyte hypertrophy and fat accumulation in extra-adipose tissues such as liver and muscle tissues, leading to increased oxidative stress and release of cytokines, such as TNFα, interleukin (IL)-6, and IL-1β." (PMID 33922045, 2021). "A prominent feature of HFD-triggered hyperlipidemia is the accumulation of lipid, as well as promoting low-grade chronic inflammation associated with increased levels of mediators such as IL-1β, IL-6, and TNF-α." (PMID 32089647, 2020). "CHD patients have higher plasma TNF-α levels than healthy people, patients who suffer from hyperlipidemia also have high serum concentrations of TNF-α, and TNF-α concentrations are positively associated with VLDL-C concentrations and negatively associated with HDL-C concentrations." (PMID 27619170, 2016). "The author’s previous findings had shown that serum and gingival crevicular fluid (GCF) proinflammatory cytokines such as TNF-α, IL-1b, and IL-6 levels may play an important role in association with a periodontal disease and hyperlipidemia." (PMID 26666260, 2015). "Hyperlipidemia may activate astrocytes by means of high levels of TG that will have direct toxic effects on the cerebral vessels and neurons by causing the secretion of TNF-α and IL-1 in the brains of rats." (PMID 28143622, 2017). "Pro-inflammatory cytokines such as IL-1β, TNF-α, and IL-17 disrupt systemic lipid homeostasis by suppressing lipoprotein lipase and promoting hepatic lipogenesis, leading to hyperlipidemia." (PMID 41508030, 2026). "TNFα has been demonstrated to promote hyperlipidemia as well as suppress fatty acid oxidation in liver as well as regulate lipid metabolism in several other tissues." (PMID 40766326, 2025). "Experimental studies indicate that asprosin can trigger proinflammatory responses in THP-1 macrophages, increasing secretion of TNF-α, IL-1β, IL-6, IL-8, and IL-12, and promotes hyperlipidemia-induced endothelial inflammation via NF-κB signaling." (PMID 41286678, 2025). "Hyperlipidemia can potentially instigate enduring inflammation in the body, promoting the secretion of inflammatory agents like tumor necrosis factor-α (TNF-α) and interleukin-6 (IL-6)." (PMID 38831342, 2024). "The rat models successfully replicated conditions of ovariectomy and hyperlipidemia, leading to pronounced release of the inflammatory cytokine TNF-α and substantial impairment of bone biomechanics." (PMID 38970109, 2024). "This is most likely due to hyperlipidemia and the expression of S100 proteins and inflammatory mediators such as interleukins and TNF-α following injury to the tunica intima after angioplasty." (PMID 38333571, 2024). "The promotion of hyperlipidemia by TNF-α is primarily mediated by stimulation of hepatic lipid synthesis and adipose lipolysis, along with suppression of triacylglycerol clearance and inhibition of insulin-stimulated de novo lipogenesis (in adipose tissue)." (PMID 39204094, 2024).
hyperlipidemia (continued). "Inhibited fat accumulation and body weight, hyperlipidemia; reduced LPS level; decreased levels of TNF-α and IL-1β; increased acetate and butyrate production; inhibited LPS/TLR4/NF-κB signaling pathway." (PMID 36671814, 2023). "With the condition of IR, hyperlipidemia increased the IL-1β and TNF-α levels further, and they were reduced by pre-treatment with TIIA." (PMID 36279396, 2022). "Statins avert smooth muscle cell relocation and spread and obstruct the stimulation of tumor necrosis factor-alpha (TNF-alpha), interleukin 1 (IL-1) beta, and other interleukins, which contribute to inflammation, a common symptom of hyperlipidemia." (PMID 34401212, 2021). "Dealing with hyperlipidemia, fenofibrate decreased TNFα and IFN-γ, but the levels had increased in PPARα knockout mice." (PMID 33603777, 2021). "Higher blood glucose levels and hyperlipidemia would lead to the activation of Adam17 that, in turn, stimulates TNF-α shedding and activation." (PMID 34884897, 2021). "Hyperlipidemia resulted in higher serum concentrations of TNF-α and IL-6, but LHD and atorvastatin treatment significantly reduced the expression of inflammatory factors." (PMID 34881240, 2021). "It was suggested that TUG1 promoted hyperlipidemia and inflammatory cytokines such as IL-6 and TNF-α by sponging miR-133a, which targeted the fibroblast growth factor 1 (FGF1) in ox-LDL-treated RAW264.7 cells." (PMID 32082313, 2020). "For these reasons, TNFα expression is positively correlated with body mass index, hyperlipidemia, insulin resistance, and glucose intolerance." (PMID 29409496, 2018). "Hyperlipidemia can induce systemic inflammation and increase the NF-κB signaling and TNF-α and IL-1β expression in animals." (PMID 30050930, 2018). "Studies have shown that hyperlipidemia can stimulate microglia, astrocytes, and other central immune cells to secrete a variety of cytokines (IL-1, TNF-α) exerting direct and toxic effects on the brain." (PMID 29409499, 2018). "Pro-inflammatory genes (TNF-α and IL-6) have been reported to be expressed at high levels and contribute to kidney injury in hyperlipidemia." (PMID 30049280, 2018). "Pro-inflammatory genes (TNF-α and IL-6) have been reported to be expressed at high levels and contribute to cardiac damage in hyperlipidemia." (PMID 30526612, 2018). "The presence of hyperlipidemia further increased the presence of IL-1 β, IL-6 and TNF in the SM in the OA-HFD group in comparison to the OA group." (PMID 29191221, 2017). "The results showed that hyperlipidemia stimulated the excessive expression of TNF-α and IL-1β in serum of myocardial I/R group." (PMID 27731393, 2016). "All HSYA groups ameliorated the excessive production of TNF-α and IL-1β in serum induced by MI/R+hyperlipidemia injury." (PMID 27731393, 2016). "All HSYA groups ameliorated the excessive production of TNF-α and IL-1β in rat hearts induced by MI/R superimposed on hyperlipidemia injury." (PMID 27731393, 2016). "Meanwhile, MI/R+hyperlipidemia group had significantly higher levels of TNF-α and IL-1β in serum than I/R group (P < 0.01)." (PMID 27731393, 2016). "Meanwhile, MI/R+hyperlipidemia group demonstrated significantly higher levels of TNF-α and IL-1β in rat hearts than I/R group (P < 0.01)." (PMID 27731393, 2016). "In the present study, XZK was shown to reduce the serum expression levels of TNF-α and IL-6 in the hyperlipidemia rat model." (PMID 25371725, 2014). "Expressions of free-fatty-acid transporters were also claimed to be reduced, resulting in reduced FFA uptake, which leads to hyperlipidemia—all in the course of TNFα's actions." (PMID 24324517, 2013). "Evidence in rodent models indicates that TNF-alpha induces hyperlipidemia by increasing hepatic triglyceride production." (PMID 23113919, 2012). "After drug administration, ATO and BA significantly reduced IL-6 and TNF-α levels (p < 0.01), suggesting that BA could alleviate systemic inflammation during hyperlipidemia development." (PMID 40529499, 2025).
hyperlipidemia (continued). "On the other hand, hyperlipidemia also increases the amount of IL-1β and TNF-α." (PMID 40141192, 2025). "In rats with hyperlipidemia, the supplementation of sea buckthorn berries enhances the expression of eNOS as well as the activity of endogenous antioxidant enzymes which suppresses TNF‐α." (PMID 37457144, 2023). "A prospective study including 31 patients with biopsy-proven NAFLD complicated with hyperlipidemia showed that atorvastatin therapy (10 mg daily for 24 months) improved adiponectin, tumor necrosis factor-alpha, transaminase, LDL cholesterol, type IV collagen, and CT liver–spleen ratio." (PMID 37374110, 2023). "Indeed, we measured increased serum TNFα concentration in response to hyperlipidemia, however, only in the male group." (PMID 33919597, 2021). "In addition, LHD treatment improved cardiac function, reduced hyperlipidemia-induced inflammatory infiltration in cardiomyocytes and suppressed the release of interleukin-6 (IL-6) and tumor necrosis factor-α (TNF-α)." (PMID 34881240, 2021). "However, TUG1 promoted hyperlipidemia and inflammatory cytokines such as IL-6 and TNF-α via sponging miR-133a." (PMID 32082313, 2020). "Furthermore, DT administration to VSMCs derived from SM22α-DTR mice causes release of IL-6, MCP-1 and GM-CSF in culture, and in the presence of hyperlipidemia, increases serum levels of TNF-α and IL-6 in vivo." (PMID 32627119, 2020). "In addition, HFD-induced hyperlipidemia mice liver tissues showed an increased mRNA level expression of TNF-α, IL-1β, and IL-8." (PMID 31952262, 2020). "MG induced Nrf2/HO-1 signaling, diminished Tylo-induced hyperlipidemia, oxidative stress, IL-1β as well as TNF-α and IL-6 that might arise from the suppression of NLRP3 inflammasome." (PMID 32992548, 2020). "Specifically, systemic exposure to infectious challenges such as bacterial lipopolysaccharide can result in the release of inflammatory cytokines including interleukin-1 (IL-1) and tumour necrosis factor alpha (TNF-α) that alter fat metabolism and promote hyperlipidaemia." (PMID 31387283, 2019). "From the point of view of inflammation, pro-inflammatory genes Tumor Necrosis Factor-α (TNF-α) and Interleukin-6 (IL-6) have been reported to be expressed at high levels and contribute to cardiac damage in hyperlipidemia, in addition to canonical inflammatory markers, such as IL-18 and IL-1β." (PMID 31635164, 2019). "Hyperlipidemia leads to the increased release of TNF-α and macrophages accumulation in plaques." (PMID 30125282, 2018). "We surmise therefore that the large number of astrocytes that proliferated released an excess of inflammatory cytokines (IL-1, TNF-α), resulting in damage to the cerebral vascular endothelial cells and neurons; this result increased in correlation with the duration of hyperlipidemia in the rats." (PMID 28143622, 2017). "Meanwhile, hyperlipidemia up-regulated the expression level of cardiac TNF-α and IL-1β." (PMID 27731393, 2016). "In addition, the levels of TNF-α were higher in the hyperlipidemia group than in the healthy control rats, demonstrating that hyperlipidemia causes the upregulation of proinflammatory cytokines and leads to liver tissue damage." (PMID 25371725, 2014). "This implies that TNFα also controls the escalations in lipolysis that lead to hyperlipidemia." (PMID 24324517, 2013). "The possible reason for increased E-selectin level might be the presence of hyperlipidemia which is reported to enhance the secretion of IL‒6 and TNF-alpha." (PMID 23830064, 2013). "The decrease in TNFα mRNA expression and secretion in response to simulated hyperlipidemia (24 h incubation with palmitate) is unexpected, considering the systemic inflammation in T2D and that TNFα secretion increases in response to a classical activation of microglia cells." (PMID 23259618, 2012).